CDH11 (cadherin 11)
Diseases named in the same sentence as CDH11 in open-access papers (continued):
Sharing a sentence is not in itself a finding about the gene and the disease.
cancer (continued). "In other cancer types, CDH11 has been reported to activate the WNT/β‐catenin pathway, which regulates mitochondrial activity." (PMID 41263259, 2025). "CDH11 is a member of the cadherin family, a transmembrane protein involved in cell adhesion, and it suppresses cancer activity via the Wnt/β‐catenin, AKT/Rho A, and NF‐κB signaling pathways." (PMID 41263259, 2025). "RANKL-OPG signaling is renowned for its importance in osteoclastogenesis, whilst CDH11 is an important molecule for the activation of the osteoblast, being critical for cancer cells to colonize the bone." (PMID 39100096, 2024). "A recent study demonstrated that cadherin-11 mediates the formation of adherence junction between cancer cells and fibroblasts." (PMID 38730588, 2024). "The results of the gray values from the western blot assay indicate that the expression of CDH11 protein in the OSCC samples was remarkably higher than that in the adjacent non-cancer oral tissues (p < 0.05), which was consistent with RT-qPCR results." (PMID 37013637, 2023). "The expression value from the RT-qPCR showed significantly higher CDH11 expression in the OSCC tissues when compared with the non-cancer oral tissues (p = 0.019)." (PMID 37013637, 2023). "The expression levels of CDH11 in OSCC patients contrasted with non-cancer groups was evaluated by integrating multi-center microarrays, a RNA-seq dataset, and in-house RT-qPCR data." (PMID 37013637, 2023). "In this sense, several authors have reported that paxillin, α-adducin, α-parvin, and cadherin-11 are altered in various types of cancer, including BC." (PMID 37686651, 2023). "Lithium inhibition of GSK3β suppresses cadherin-11, which is involved in cell–cell adhesion, cancer cell invasion, and metastasis of cancer." (PMID 36836894, 2023). "In OvCa, CDH11 is connected to advanced stage and nodal involvement, in addition to migration and metastasis, yet displays limited involvement in cancer progression." (PMID 36233808, 2022). "Cadherin-11 is abundant in osteoblasts, and it has been demonstrated to promote metastasis primarily to the bone, at least in breast and prostate cancer." (PMID 35411090, 2022). "CDH11 often leads to promoter methylation inactivation, which can induce cancer cell apoptosis, suppress cell motility and invasion, and can inhibit cancer through Wnt/β-catenin, AKT/Rho A and NF-κB signaling pathways." (PMID 33442417, 2021). "Meanwhile, HEYL enhances carcinogenesis and metastasis through activating cancer‐related signaling pathways by regulating CDH11 expression level in GC cells." (PMID 32463580, 2020). "Mesenchymal markers snail and MMP14 were upregulated in cancer cells maintained in 3D (P < 0.001), cadherin-11 was downregulated (P < 0.001) and HER2 increased (P < 0.05)." (PMID 32694700, 2020). "CDH11 has been reported to play a dual role in the occurrence and development of various types of cancer." (PMID 32685527, 2020). "Previous studies have demonstrated CDH11 controls cell fated decisions and promotes cancer development." (PMID 32463580, 2020). "Our initial investigation into the role of CDH11 during early embryogenesis stemmed from its expression in developing NC cells and the varied accounts of its function in cancer cells." (PMID 33192560, 2020). "In our study, according to the close relationship between CDH11 and macrophages, especially the M2 phenotype, we can infer that CDH11 contributes to helping cancer cells escape the immune response." (PMID 32685527, 2020). "CDH11 is known to play a role in NC cell migration in amphibian embryos as well as cell survival, proliferation, and migration in cancer cells." (PMID 33192560, 2020). "Cadherin 11 is a transmembrane protein with documented conflicting roles in several types of cancers." (PMID 30691241, 2019).
cancer (continued). "The present results suggest that the EPHB6 mutation and its downstream EPHA2/JNK/CDH11/RhoA/FAK signaling axis are novel diagnostic and therapeutic targets for overcoming paclitaxel resistance in cancer patients." (PMID 31160603, 2019). "CDH11 is a cell adhesion molecule that activates the formation of cytoskeletal actin stress fibers, increasing the metastatic potential of cancer cells." (PMID 31160603, 2019). "We also demonstrated, for the first time to the best of our knowledge that exposure to anti-CDH11 antibody suppresses metastasis, reduces CDH11, FN and β-catenin expression, and abrogate the cancer stem cell (CSC)-like traits of MBC cells." (PMID 31248373, 2019). "Previously, we showed that ZEB2 cooperates with the transcription factor Sp1 to function as a transcriptional activator of vimentin, integrin α5, and cadherin-11, which promotes cancer cell invasion." (PMID 29416649, 2018). "Cadherin-11 and connexin 43 were highly expressed when osteoblasts and cancer cells were cocultured." (PMID 28303941, 2017). "The cadherin switch, which is an increase in the expression of N-cadherin and/or cadherin 11 and a decrease in E-cadherin, is associated with both the epithelial-to-mesenchymal transition (EMT) and cancer progression." (PMID 29296180, 2017). "Given the importance of CDH11 in breast tumorigenesis, there is little knowledge on how the expression of CDH11 is controlled in cancer cells." (PMID 24810778, 2014). "Because CDH11 is often only detected in aggressive cancer cell lines and tissues and ectopically expressing CDH11 can effectively enhance cancer cell migration and metastasis, CDH11 has been regarded as a metastasis promoter." (PMID 24810778, 2014). "The work presented here confirms the association of CDH11 with a number of malignancies and demonstrates that CDH11 is an important driver of certain poor prognosis cancers, as it is in RA." (PMID 24681547, 2014). "This cadherin 11 up-regulation is thought to promote cellular interactions between cancer cells and cadherin 11 expressing osteoblasts that is typical of bone metastasis." (PMID 23359820, 2013). "To further demonstrate the presence of CDH11 5′-CpG island methylation in metastatic cells, we undertook bisulphite genomic sequencing analyses of multiple clones in the described cancer cell lines." (PMID 22374749, 2012). "As an example, an EI was found near the transcription start sites (TSSs) of the cadherin 11 gene (CDH11), of which epigenetic disruption was associated with metastasis of human cancers." (PMID 23102236, 2012). "Among miR-204 gene targets that are potential regulators of cell-matrix interaction and proteolysis, overexpression of APRC1B, CTSC, FAP, MMPs, BMP1, CDH11 and ITGB4 is associated with cancer metastasis and/or poor prognosis." (PMID 20369013, 2010). "Cadherin-11 is also specifically expressed in fibroblasts and cancer cells that have undergone EMT." (PMID 38730588, 2024). "Targeting these specific immune cell subtypes or genes differentially expressed in these immune subpopulations as a result of Cdh11 deficiency may be an effective therapeutic strategy to treat Cdh11-expressing cancers and fibrotic disease." (PMID 37954069, 2023). "In particular, the majority of cancers including breast (6/6), brain (18/18), adrenal gland (4/4), lung (21/23), lymph node (12/12), ovary (16/17) and testis (9/9) exhibited high occurrence of nuclear CDH11." (PMID 37558205, 2023). "Most notably, our current results show that CDH11 co‐localizes with β‐catenin in the nucleus, while depletion of CDH11 or inhibition of CDH11 cleavage diminishes Wnt activation with a concomitant decrease in the proliferation, migration and invasion capacity of cancer cells." (PMID 37558205, 2023). "Furthermore, the administration of a small molecule inhibitor blocking Cdh11 increased the efficacy of gemcitabine, a common anti-cancer chemotherapeutic." (PMID 37954069, 2023).
cancer (continued). "We also observed low Cdh11 expression in cancer cells undergoing EMT in both mice and human PDAC." (PMID 37954069, 2023). "The increased presence of CDH11 in the peripheral blood of cancer patients may be indicative of an advanced disease state." (PMID 37954069, 2023). "As altering CDH11 affects cell survival, CDH11 may be functioning as it does in cancer cells, as pro-apoptotic stemness modulator that functions via the WNT and Rho pathways." (PMID 33192560, 2020). "Although we could not detect this isoform in CAF-S1 cellular extracts and corresponding supernatants, we could hypothesize that CDH11 secreted isoform might be involved in the distant effect of CDH11 on cancer cell migration." (PMID 32665033, 2020). "Finally, corroborating the in silica and in vitro findings, in vivo assays showed that the administration of anti-CDH11 antibody or miR-335 mimic suppressed tumorigenesis and inhibited cancer metastasis." (PMID 31248373, 2019). "CDH11 has been reported to play an important role in cancer metastasis and inflammatory arthritis." (PMID 31269038, 2019). "A strong positive correlation was also established between the expression CDH11 and metastasis-associated genes, β-catenin and vimentin in MCF7 and MDA-MB-231 cells in the presence of cancer-associated fibroblasts (CAFs), suggesting enhanced metastatic potential." (PMID 31248373, 2019). "Importantly, the expression differences between the cancer specimens and normal tissues were all statistically significant for CDH11 (P < 0.0001), ILF3 (P = 0.017) or HOXC8 (P = 0.004)." (PMID 29296180, 2017). "While studies have shown how type I classical cadherin fragments can mediate this process in cancer cells, our data show how the shed fragment of the type II classical cadherin, cadherin-11, can promote this process in CNC cells by interacting with ErbB2 to increase Akt activity." (PMID 29190819, 2017). "CDH11 is a major target in RA, an inflammatory disease frequently compared with cancer." (PMID 24681547, 2014). "The presence of a few CDH11 methylated clones in both primary cancer cell lines might suggest that the metastasis might have arisen from those cells." (PMID 22374749, 2012). "Here we show that cell density and GSK-3β regulate cadherin-11 levels in cancer cells." (PMID 19274078, 2009). "Also, Cdh11 deficiency induced immune memory in Cdh11-/- mice that cleared tumors; these mice did not form new tumors upon subsequent re-challenges with the same cancer cells." (PMID 37954069, 2023). "CDH11 is known as a transmembrane protein mediating cellular adhesion and a hallmark of mesenchymal phenotype that is broadly expressed in multiple cell types undergoing EMT including breast, prostate, brain, renal, bone, bladder, ovary and gastric cancer cells." (PMID 37558205, 2023). "However, CDH11 was also reported to suppress metastasis in certain cancers." (PMID 33391403, 2021). "Additionally, the role of CDH11 in cancer cells is variable." (PMID 33192560, 2020). "In conclusion, the present results suggest that the EPHB6 mutation promotes cancer cell proliferation and migration/invasion and induces CAM-DR, and these effects are mediated by the stabilization of EPHA2 and the activation of downstream JNK/CDH11/RhoA/FAK signaling." (PMID 31160603, 2019). "Taken together these data suggest that, in addition to other suggested celecoxib targets such as survivin, the ER stress response and PDK1, CDH11 may play a role in mediating the COX-2 independent effects of the CelebrexTM family of anti-inflammatories in cancer and in RA." (PMID 24681547, 2014). "Cadherin-11 may mediate the binding of cancer cells to osteoblasts." (PMID 25566502, 2014). "Thus, cadherin-11 is likely an important determinant of bone-tropism in cancer cells." (PMID 25566502, 2014). "YTHDF1 promotes migration, invasion, and osteoblast adhesion and induces osteoclast differentiation of cancer cells in vitro and in vivo by inducing EZH2 and CDH11 translation." (PMID 39185313, 2024).
cancer (continued). "CDH11 is a cell adhesion molecule involved in the epithelial-mesenchymal transition (EMT), a critical process in cancer metastasis and drug resistance." (PMID 39309859, 2024). "Detection of differential markers subtyped the cells of mesenchymal origin (vimentin, desmin, cadherin-11, podoplanin, CD74, S100A4, CD44, FAP), which vary according to the functional differentiation and specialization in sites of cancer tissue." (PMID 39575252, 2024). "This is the first study evaluating the expression significance of CDH11 in OSCC and non-cancer oral samples via various detection methods." (PMID 37013637, 2023). "Out of 84 cancer metastasis–related genes, 19 were upregulated by sevoflurane exposure, but only 2 (TIMP-2 and Cadherin-11; CDH11) were upregulated by propofol exposure relative to the NC (n = 3)." (PMID 35953652, 2023). "Among these genes, cadherin-11 (OB-cadherin), a homophilic calcium-dependent cell adhesion molecule, and MTA1, a histone deacetylase, have been implied in metastasis of various cancer." (PMID 36230825, 2022). "In BC cells, the oncogene BCL6 and cancer progression-related genes ROCK2 and CDH11 have been identified as targets of miR-127 in BC." (PMID 36371182, 2022). "In BC cells, miR-30 inhibition enhances tumorigenesis and metastasis by targeting UBC9 and ITGB3 and osteomimicry of cancer cells by targeting RUNX2, ITGA5 and CDH11." (PMID 33800656, 2021). "The fluorescent cancer cells were isolated by FACS, lysed, and analyzed for their E-cadherin and cadherin-11 protein and mRNA levels." (PMID 32752204, 2020). "In contrast to the gradual increase of VE-cadherin expression in cancer cells, the protein amounts of E-cadherin in MCF7 and cadherin-11 in MDA-MB-231 cells decreased significantly after 24 h of co-culturing." (PMID 32752204, 2020). "Cadherin-11 (CDH11), also known as osteoblast cadherin, has been assigned a wide range of roles in relation to its influence on cancer cell behavior." (PMID 23971040, 2013). "However, the expression of the PDGFRA, PDGFRB, CDH11, and EMILIN1 genes was mainly reduced in fibroblasts after co-cultivation with cancer cells." (PMID 36263012, 2022). "After 3 days of co-culture, CAF-S1 primary fibroblasts tended to increase MCF7 and T47D proliferation, although without reaching significance; and CDH11 silencing in CAF-S1 had no impact on the total number of cancer cells." (PMID 32665033, 2020). "The coding genes affected by this epigenetic lesion cover all the molecular pathways related to cancer biology, such as DNA repair (BRCA1, MHL1 and MGMT), cell cycle (p16INK4a and p15INK4b), apoptosis (DAPK and TMS1) or cell adherence (E-cadherin and cadherin-11)." (PMID 30018746, 2018). "The products of several genes from our potential cell surface list are suspected of playing key roles in more general cancer-related activities such as immunosuppression/evasion (CD14 and CD86), cell migration (ICAM, CDH11) and proliferation (TGFB1, PMEPA1, PDGFRL, SLC19A3)." (PMID 27363029, 2016). "The presence of CpG island hypermethylation of CDH11 was not a specific feature of the metastasis cancer cell lines or an in vitro phenomenon." (PMID 22374749, 2012). "For example, the deletion of the chromosome 16, the 19q13.2–19q13.43 regions, and the chromosome 21 are significantly correlated with underexpression of candidate cancer-suppressor genes, respectively CBFB or CDH11, TFPT and DSCR1, giving additional evidence in support of these events." (PMID 20711339, 2010). "Cadherin 11 (CDH11) and TGFβ receptor 2 (TGFBR2), showing increased abundance in the basal-like cell line MDA-MB231 after co-culture, but not in the MCF7 luminal-like cell line, might suggest a differential influence of NPC interaction with cancer subtypes." (PMID 39232464, 2024).
cancer (continued). "Previous research has shown that inhibition of Cadherin 11 (CDH11)—the expression of which is correlated with shorter survival in TNBC—can downregulate β-catenin, which suppresses the canonical Wnt signaling pathway, thereby inhibiting the cancer stem-like phenotype in TNBC." (PMID 35805056, 2022). "Similarly, the survival rate of these two cancer cell lines was not affected by CDH11 silencing in CAF-S1 cells." (PMID 32665033, 2020). "However, low mRNA levels of CDH11, ILF3 or HOXC8 were evident in cancer stage 0." (PMID 29296180, 2017). "COL6A3, COL8A1, CDH11, and CXCL12 were not expressed in either PDAC tissues or normal tissues, and BGN and THBS2 were overexpressed in both cancer and normal tissues." (PMID 33282565, 2020).
infection (5 papers, 2012 to 2021). The state of being infected such as from the introduction of a foreign agent such as serum, vaccine, antigenic substance or organism. "As infection continues, at 90DPI, Angiomotin like-1 (component of tight junctions) and other adherens junction proteins such as cadherin 11, 23, catenin alpha 1 and FAK also displayed significantly decreased expression." (PMID 23593167, 2013). "Hence the reduction in infection is due to the targeted nanoparticles via cadherin-11." (PMID 32275737, 2020).
psychiatric diseases (2 papers, 2021 to 2022). "Several recent genetic studies have implicated two type II cadherins, CDH11 and CDH9, in ASD and other psychiatric diseases." (PMID 34523068, 2022).
digestive system cancer (1 paper, 2025). A primary or metastatic malignant neoplasm involving any part of the digestive system. "After comparing the co-expressed genes in these five digestive system cancers, five genes, PKD2, CDH11, OSMR, ITGB1, and BNC2, were further identified as being associated and interacting with ITGAV through the Venn diagram." (PMID 40018050, 2025).
CDH11 also shares sentences with these, for which no sentence is quoted: scleroderma (4 papers); adenocarcinoma (3); fibrosis (3); hepatocellular carcinoma (3); alcohol dependence (2); aortic valve calcification (2); Astrocytoma (2); autism spectrum disorder (2); bipolar disorder (2); idiopathic pulmonary fibrosis (2); lymphoma (2); pancreatic ductal adenocarcinoma (2); renal fibrosis (2); acromegaly (1); acute myeloid leukemia (1); adenoid cystic carcinoma (1); alcoholism (1); aortic valve stenosis (1); atrial fibrillation (1); autoimmune disease (1); bone cysts (1); bone metastasis (1); carcinoid tumor (1); cardiac hypertrophy (1); cardiovascular diseases (1); cartilage disorders (1); cholangiocarcinoma (1); chordoma (1); cocaine addiction (1); colon adenocarcinoma (1).
A further 35 diseases each share a sentence with CDH11 in 1 paper.